IL1B (interleukin 1 beta)
Diseases named in the same sentence as IL1B in open-access papers (continued):
Sharing a sentence is not in itself a finding about the gene and the disease.
rheumatoid arthritis (688 papers, 2004 to 2026). A chronic, systemic autoimmune disorder characterized by inflammation in the synovial membranes and articular surfaces. "Research has established a close association between IL-1β and numerous inflammation-related conditions, including neurodegenerative diseases, chronic obstructive pulmonary disease, and rheumatoid arthritis." (PMID 40238913, 2025). "Overproduction of IL-1β is linked to pathophysiological alterations in diseases such as rheumatoid arthritis, neuropathic pain, inflammatory bowel disease, osteoarthritis, vascular disease, multiple sclerosis, and Alzheimer’s disease." (PMID 39937257, 2025). "rs1800896 (IL10) and rs1143634 (IL1B) have been associated with rheumatoid arthritis and inflammatory bowel disease." (PMID 41346622, 2025). "In murine models, the deficiency of MMP8 increases the severity of rheumatoid arthritis, leading to a greater expression of IL-1β." (PMID 40299554, 2025). "For instance, it has been shown that higher levels of IL‐1β in younger ages (4 to 17 years‐old) were associated with future risk of rheumatoid arthritis, inflammatory bowel disease, and osteopenia in adults." (PMID 40901647, 2025). "Our study also reports that Vigeo inhibited arthritis symptoms, including bone loss and serum levels of TNF-α, IL-6, and IL-1β, in a mouse model of collagen-induced arthritis/rheumatoid arthritis." (PMID 39203823, 2024). "Changes in IL-1β functions have been implicated in various diseases, including rheumatoid arthritis, type 2 diabetes, and Alzheimer’s disease." (PMID 38397895, 2024). "In this study, we used LPS and IL-4 to induce macrophage to M1 and M2 macrophages to investigate the mechanisms underlying the therapeutic effects of IL-1β-hUCMSCs on macrophage polarization and macrophage apoptosis in rheumatoid arthritis." (PMID 37391581, 2023). "IL-1ra blocks signals of IL-1β, a potent proinflammatory cytokine that is implicated in the development of chronic inflammatory disorders such as type 2 diabetes, rheumatoid arthritis, and cardiovascular diseases." (PMID 37174632, 2023). "In rheumatoid arthritis, the chronic inflammation of synovial cells is largely caused by IL-1β overproduction; this directly activates FLS and leads to joint destruction and bone resorption." (PMID 37123081, 2023). "The IL1B promoter SNP rs16944 has been widely studied with reported associations with many diseases including lung cancer, rheumatoid arthritis and myocardial ischaemia." (PMID 35994463, 2022). "In particular, up-regulation of IL-1R1 via its agonistic ligands consisting of IL-1β and IL-1α is implicated in a variety of human diseases, such as rheumatoid arthritis, psoriasis, type I diabetes, amyotrophic lateral sclerosis, and dry-eye disease." (PMID 35523814, 2022). "More importantly, blocking IL-1β signaling of all sources would increase the risk of infection, which has long been noted in anakinra’s application for rheumatoid arthritis." (PMID 36160384, 2022). "This variant is a gain-of-function mutation that leads to an increased production of IL-1β, which is associated with various inflammatory diseases such as rheumatoid arthritis, Crohn’s disease, and celiac disease." (PMID 36553538, 2022). "The iNOS and COX-2 expressions are controlled by pro-inflammatory cytokines, such as TNF-α, IL-1β, and IL-6, which are implicated in numerous autoimmune and inflammatory diseases, including rheumatoid arthritis, uveitis, and sclerosis." (PMID 35877707, 2022). "When dysregulated, however, IL-1β also underlies the pathology observed in several inflammatory diseases including toxic shock syndrome, rheumatoid arthritis, and type 2 diabetes." (PMID 34650553, 2021). "TNF-α and IL-1β are the highly substantial inflammatory mediators reported in association with several inflammatory diseases including rheumatoid arthritis, bacterial sepsis, skin inflammation and many others." (PMID 33933037, 2021).
rheumatoid arthritis (continued). "Anti-TNF-α therapy in patients with rheumatoid arthritis leads to the reduction of other pro-inflammatory mediators, such as IL-1β and IL-6, causing an improvement in the anti-inflammatory effect." (PMID 34959607, 2021). "PGE2, IL-6, IFN-β, and IL-1β have been implicated in inflammatory and autoimmune diseases, including rheumatoid arthritis and systemic lupus erythematous." (PMID 32290603, 2020). "Currently, IL-1β blockage has been therapeutic strategies for autoimmune and autoinflammatory diseases such as rheumatoid arthritis, cryopyrin-associated periodic syndromes, gout and type II diabetes mellitus." (PMID 31900383, 2020). "Excessive and persistent activation of the NLRP3 inflammasome leads to loss of the control of IL-1β processing and contributes to several immune diseases, such as rheumatoid arthritis, systemic lupus erythematosus, gout and colitis." (PMID 33542692, 2020). "IL-1β is implicated in the pathophysiology changes that occur during different disease states, such as rheumatoid arthritis, inflammatory bowel disease, vascular disease, and so forth." (PMID 30463239, 2018). "IL-1β is associated with various inflammatory diseases such as rheumatoid arthritis, auto-inflammatory diseases, etc. and IL-1β neutralization is mostly used for inhibiting inflammation." (PMID 29281705, 2017). "This work is also supported by various studies in mouse model of trauma, Caucasian and Chinese population that indicated that IL-1β polymorphism are associated with many diseases including inflammatory bowel disease, rheumatoid arthritis and gastric cancer." (PMID 26561011, 2015). "Various reports have indicated that cytokines such as TNF-α, IL-1β and IL-6 play key roles in driving the inflammation and synovial cell proliferation characterizing rheumatoid arthritis-associated joint destruction." (PMID 25229347, 2014). "Despite of the good efficacy of biologic agents such as TNF-α or IL-1β blocker for many patients with rheumatoid arthritis, augmented risk of some adverse side effects such as infection and malignancy still persist in concern." (PMID 25229347, 2014). "The progression of rheumatoid arthritis is accelerated by proinflammatory cytokines and chemokines, and tumor necrosis factor-α (TNF-α) and interleukin-1β (IL-1β) are reported to be associated with the progression of rheumatoid arthritis." (PMID 23442977, 2013). "Inflammasome activation and IL-1β overproduction have been implicated in the pathogenesis of a number of diseases, including type 2 diabetes, gout, and rheumatoid arthritis." (PMID 22348744, 2012). "Genetic variations in IL1RN, IL1A and IL1B have been associated with ulcerative colitis, gastric cancer and rheumatoid arthritis." (PMID 22322675, 2012). "IL-1β has been shown to break peripheral tolerance by facilitating the expansion of effector T cells and is implicated in autoimmune diseases such as rheumatoid arthritis." (PMID 21779356, 2011). "Additionally, abnormal expression or excessive activation of IL-1β is associated with the onset and progression of various diseases such as rheumatoid arthritis, inflammatory bowel disease, among others." (PMID 40857330, 2025). "Increased glycated TTR and RAGE protein levels have been found in patients suffering from rheumatoid arthritis, in association with increased levels of the pro-inflammatory cytokines IL-1β, IL-6, and TNF-α, suggesting a role of TTR/RAGE in this inflammatory disorder." (PMID 39766257, 2024). "As recently reviewed by Spel, several SNPs in the genes encoding NLRP3, NLRP1, IL-1β, and IL-18, which lead to increased expression levels, were connected to the development of rheumatoid arthritis, gout, ankylosing spondylitis, and juvenile idiopathic arthritis." (PMID 35629398, 2022). "Recently, we could show that in rheumatoid arthritis, the increased [Ca2+]ex-induced IL-1β release of monocytes is caused, in part, by increased CaSR expression." (PMID 35931812, 2022).
rheumatoid arthritis (continued). "IL-1β has been implicated in other chronic inflammatory diseases, such as multiple sclerosis and rheumatoid arthritis, and may contribute to the spread of inflammation between the brain and peripheral tissue." (PMID 31774879, 2019). "Moreover, the amplification of the PGE2 biosynthesis pathway by HMGB1/IL-1β is suggested as an important pathogenic mechanism perpetuating inflammatory and destructive activities in rheumatoid arthritis." (PMID 31560698, 2019). "In addition to the innate immune response, the role of IL-1β has been well established in the differentiation of pathogenic Th17 cells and in different autoimmune diseases including rheumatoid arthritis (RA) and psoriatic diseases." (PMID 25876154, 2015). "Interleukin 1β (IL-1β) is considered the most important cytokine in the pathogenic process of inflammation in RA; it induces proliferation of rheumatoid arthritis synovial fibroblasts (RASFs), and production of high levels of MMPs and prostaglandin E2 (PGE2) via COX expression by RASFs." (PMID 25299270, 2014). "Rheumatoid arthritis (RA) is a chronic inflammation disease characterised by hypertrophy of the synovial membrane, ultimately causing joint damage due, in part, to the sustained production of inflammatory cytokines such as TNFα, IL-1β and IL-6." (PMID 21914218, 2011). "The inflammatory cytokines, TNF-α, IL-1β, IL-6 and IL-17 are all regulatory factors responsible for the initiation, perpetuation and destructive capacity of the rheumatoid arthritis synovium and all four have been implicated in recruitment of inflammatory cells to the joint." (PMID 19409094, 2009). "IL-1β has been implicated in the pathogenesis of rheumatoid arthritis (RA), gout arthritis, ankylosing spondylitis (AS), and adult-onset and systemic-onset juvenile idiopathic arthritis (Still’s disease)." (PMID 36613465, 2022). "IL-1β is the predominant pro-inflammatory cytokine associated with rheumatoid arthritis (RA), which has been widely used as a stimulator in RA related studies in vitro." (PMID 31835494, 2019). "In rheumatoid arthritis (RA), it is associated with increased inflammation, particularly by the acute-phase reactant IL-1Ra antagonizing IL-1β, joint destruction, and glucocorticosteroid utilization." (PMID 29623147, 2018). "For example, TNF-α inhibition and IL-1β inhibition have been successful as therapies for rheumatoid arthritis (RA) and chronic inflammatory pathologies associated with cancer, respectively." (PMID 26633296, 2015). "IL-1β is one of the main cytokines that has been implicated in the pathogenesis of degenerative joint diseases such as OA and rheumatoid arthritis (RA)." (PMID 22194879, 2011). "Subgroup analysis revealed that in rheumatoid arthritis (RA) patients, the probiotics group showed greater improvements in IL-6, IL-1β, and TNFα compared to the controls." (PMID 41978157, 2026). "The journal retracts the article titled, "Rheumatoid Arthritis-Associated MicroRNA-155 Targets SOCS1 and Upregulates TNF-α and IL-1β in PBMCs" [...]." (PMID 42007900, 2026). "IL-1β is a key cytokine in Rheumatoid Arthritis (RA), driving synovitis, cartilage degradation, and bone erosion." (PMID 41415279, 2025). "Myostatin induces pro-inflammatory cytokines, such as TNF-α and IL-1β, in rheumatoid arthritis synovial fibroblasts through distinct signaling pathways." (PMID 40427596, 2025). "Inhibitors of IL-1, such as anakinra (IL-1 receptor antagonist, IL-1ra) and canakinumab (a monoclonal antibody against IL-1β), are used to treat conditions like rheumatoid arthritis and certain autoinflammatory syndromes." (PMID 40703575, 2025). "In patients with rheumatoid arthritis, bortezomib suppresses the release of pro-inflammatory cytokines TNFα and IL-1β." (PMID 41035952, 2025).
rheumatoid arthritis (continued). "In rheumatoid arthritis patients, IL-1β induces prostaglandin E and collagenase production by synovial cells, promotes bone resorption, and upregulates the production of other pro-inflammatory cytokines, such as GM-CSF and IL-6." (PMID 40136507, 2025). "The overproduction of pro‐inflammatory cytokines TNF‐α, IL‐1β, and IL‐6 was observed in concanavalin A‐activated peripheral blood mononuclear cells and macrophages extracted from patients with rheumatoid arthritis induced by ENO1." (PMID 40586619, 2025). "Previous studies have shown that kaempferol can suppress the proliferation of both unstimulated and IL-1β-stimulated rheumatoid arthritis synovial fibroblasts (RASFs)." (PMID 40699843, 2025). "Our study offers several strengths, including the use of a physiologically relevant in vitro model of rheumatoid arthritis, in which synoviocytes were stimulated with IL-1β to mimic the inflammatory joint microenvironment." (PMID 40563345, 2025). "Spermidine, an antioxidant, can protect chondrocytes from IL-1β-mediated ferroptosis in rheumatoid arthritis." (PMID 40692793, 2025). "Estrogen deficiency post-hysterectomy may accelerate joint degeneration via upregulation of matrix metalloproteinases (MMPs) and interleukin-1β (IL-1β), pathways implicated in both OA and rheumatoid arthritis (RA) pathogenesis." (PMID 40832634, 2025). "Other comorbid disorders include type 1 diabetes, associated with IL-17 and IL-6 dysregulation, and rheumatoid arthritis, typically characterized by TNF-α and IL-1β elevation." (PMID 40430113, 2025). "It is already being used clinically in some cases of type 2 diabetes and concomitant gout or rheumatoid arthritis, for which anakinra and anti-IL-1β antibodies are approved." (PMID 39496966, 2025). "Canakinumab, a human IgG1 anti-IL-1β monoclonal antibody initially approved for rheumatoid arthritis, has been successfully repurposed for MWS, an autoinflammatory rare disorder caused by increased IL-1." (PMID 39773231, 2025). "The expression of CCL-23 mRNA was found in monocytes stimulated with IL-1β and IL-4 and can also be detected in SFs from patients with rheumatoid arthritis." (PMID 40083631, 2025). "Several studies have shown that blocking the effects of IL-1β in rheumatoid arthritis protects bone and cartilage." (PMID 40136507, 2025). "Mimicking in vitro a rheumatoid arthritis microenvironment with synoviocytes exposed to IL-1β, the present study shows that HA can synergistically interact with XAN and/or EGCG to target NF-κB and attenuate the inflammatory cell response." (PMID 40563345, 2025). "Under inflammatory conditions in rheumatoid arthritis (RA), several molecules such as IL-1β, IL-6, TNF-α, IL-17, and hypoxia-inducible factor-1α (HIF-1α) are produced, which can mediate bone loss." (PMID 40153574, 2025). "For example, expression ofinterleukin-1 beta (IL1B) is increased in rheumatoid arthritis, which is reflected in the ANDSystemknowledge base as an “expression upregulation” relationshipbetween RA and the IL1B protein." (PMID 41536794, 2025). "A study by Zunhua Shu showed that fucoidan inhibited survival and induced apoptosis in IL-1β-treated rheumatoid arthritis fibroblast synoviocytes." (PMID 38164477, 2024). "SOF also significantly diminished the serum level of TNF-α and IL-1β in rheumatoid arthritis, and cisplatin-induced nephrotoxicity." (PMID 38874805, 2024). "MMPs are overexpressed in conditions like rheumatoid arthritis, along with interleukin 1β (IL-1β), interleukin 6 (IL-6), and chemokines." (PMID 39766566, 2024). "For instance, in the serum-transferred K/BxN arthritis model, there was an observed increase in spinal IL-1β mRNA levels, whereas IL-6 levels remained unchanged, even though a trend towards higher IL-6 CSF levels was observed in rheumatoid arthritis patients." (PMID 38419042, 2024).
rheumatoid arthritis (continued). "Abundant accumulating succinate from macrophages activated by inflammatory signals in the synovial fluids from rheumatoid arthritis patients enhanced IL-1β production and release, perpetuating inflammation." (PMID 38291510, 2024). "Anakinra and canakinumab are IL-1β inhibitors currently used clinically to treat autoimmune diseases such as rheumatoid arthritis and early-onset multisystem inflammatory diseases." (PMID 39479463, 2024). "Similar results with response to Il-1β were obtained in an in vitro study in which the effect of exenatide on fibroblast-like synoviocytes isolated from patients suffering from rheumatoid arthritis was examined." (PMID 38339133, 2024). "IL-1RA is a naturally occurring inhibitor of IL-1β that lacks agonist activity but competitively binds to IL-1 receptors, playing a crucial role in various diseases, including rheumatoid arthritis and inflammatory bowel disease." (PMID 39479463, 2024). "The disease spectrum induced by IL-1β is broad and includes microbial infection, autoimmune disorders (Crohn’s disease, rheumatoid arthritis, systemic lupus erythematosus, etc.), osteoarthritis, neurodegenerative diseases, insulin resistance, and LGI." (PMID 38257150, 2024). "In this study, to mimic the inflammatory microenvironment of RA joint tissue, the pro-inflammatory cytokine IL-1β was used to stimulate human fibroblast-like synoviocytes-rheumatoid arthritis (HFLS-RA)." (PMID 37714911, 2023). "IL-1β is a key pro-inflammatory cytokine, primarily released by macrophages, and it is thought to play a major role in rheumatoid arthritis pathogenesis." (PMID 36678181, 2023). "Most studies on IL-1β signaling inhibition have reported that inhibition of IL-1β signaling has therapeutic effects in various inflammatory diseases such as rheumatoid arthritis, osteoarthritis, and systemic inflammatory conditions." (PMID 37079558, 2023). "Patients with systemic inflammatory disorders, such as rheumatoid arthritis, and a concurrent Zn shortage have been demonstrated to have higher levels of IL-1α, IL-1β, and IL-6 expression compared to those who consume more Zn." (PMID 37946846, 2023). "Of note, when rheumatoid arthritis synovial fibroblast (RASF) were activated by IL-1β or lipopolysaccharide (LPS), IL-8 and monocyte chemoattractant protein (MCP)-1 production increased many folds, and GLPP significantly suppressed their productions." (PMID 36985456, 2023). "Interleukin 1β (IL-1β) is a major pro-inflammatory trigger in both osteoarthritis and rheumatoid arthritis." (PMID 36899825, 2023). "Treatment with 20-hydroxyecdisone reduced TNF-α, IL-1β, IL-6 and NF-κB in rat serum in a rheumatoid arthritis model." (PMID 37687297, 2023). "IL-1β, IL-6, and TNF are three cytokines implicated in PASC and other inflammatory diseases such as rheumatoid arthritis, with IL-1 also contributing to inflammation in MS." (PMID 37112929, 2023). "Noteworthy examples include tumor necrosis factor-alpha (TNF-α), interleukin-1 beta (IL-1β), and IL-6, which are often elevated in disorders like rheumatoid arthritis (RA), intensifying inflammation and contributing to tissue damage." (PMID 37965323, 2023). "Interleukin 1beta (IL-1β) is a pro-inflammatory cytokine overexpressed in the articular cartilage during the progression of both osteoarthritis and rheumatoid arthritis." (PMID 36899825, 2023). "Silencing JMJD3 or applying GSK-J4 to inhibit the activity of JMJD3 can drastically downregulate inflammatory factors induced by IL-1β by affecting the level of H3K27me3 in the promoter in joint fibroblasts of patients with rheumatoid arthritis." (PMID 36874364, 2023). "Anakinra, an Il-1 receptor antagonist protein approved for the treatment of rheumatoid arthritis, was used to block Il-1β signaling." (PMID 37443034, 2023).